COL1A2 (collagen type I alpha 2 chain)
Diseases named in the same sentence as COL1A2 in open-access papers (continued):
Sharing a sentence is not in itself a finding about the gene and the disease.
ovarian carcinoma (continued). "Therefore, COL1A1, COL1A2, MT-CYB, CCT5, and PAPPA may be potential genetic biomarkers for the treatment of ovarian cancer." (PMID 35360863, 2022). "It is also noticed that the origins of high COL1A1, COL1A2, and COL3A1 expression positively correlate with fibroblast-specific markers (FAP) and smooth muscle actin (ACTA2), whereas COL4A1, COL4A2, and COL18A1 seem to be predominantly expressed in ovarian cancer cells." (PMID 33026975, 2020). "The immunohistochemical analysis of COL1A2, COL3A1, and COL21A1 revealed that regardless of the type of analyzed ovarian cancer subtype the expression of those proteins was present not only in the ECM surrounding the tumor (what was expected) but also in cancer cells." (PMID 30583585, 2018).
Ehlers-Danlos syndrome (18 papers, 2007 to 2025). The Ehlers–Danlos syndromes (EDS) are a clinically and genetically heterogeneous group of heritable connective tissue disorders (HCTDs) characterized by joint hypermobility, skin hyperextensibility, and tissue fragility. "COL1A2 encodes the α2 chain of type I collagen and mutations give rise to different bone diseases, including autosomal dominant OI and Ehlers-Danlos syndrome." (PMID 30042735, 2018). "Mutations in COL1A2 may cause symptoms ranging from severe OI to a milder Ehler-Danlos syndrome." (PMID 34394176, 2021). "As compared to missense or splice-site mutations, multiexon duplication or deletion in COL1A2 has less been reported in classic OI cases but it may be linked to a wide array of clinical OI phenotypes or several subtypes of Ehlers-Danlos syndrome (EDS), depending on the location of variant." (PMID 34394176, 2021). "Polymorphisms in COL1A2 and COL3A1 (which together make up 80–90% of arterial collagens) are well-established in IAs, and are known to lead to Ehlers-Danlos syndrome." (PMID 31666072, 2019). "Recently, heterozygous variants in COL1A2 gene, which usually cause osteogenesis imperfecta type II, III and IV as well as several types of Ehler-Danlos syndrome, were reported in three families with non-syndromic dentinogenesis imperfecta by Lee and co-authors." (PMID 38630328, 2024). "For instance, mutations in COL1A2, COL3A1, and COL5A2 human genes (identified as hub genes in the present research) are at least in part the genetic basis of the Ehlers-Danlos syndrome: a systemic connective tissue disorder caused by defects in fibrillar collagen deposition." (PMID 35874513, 2022).
fibrosis (17 papers, 2013 to 2025). the formation of excess fibrous connective tissue in an organ or tissue in a reparative or reactive process. "To exclude the contributions of other cells in Prrx1-mediaeted cardiac fibrosis, we generated fibroblast-specific Prrx1 gene knockout (Prrx1FB−/-) mice by crossing Prrx1flox/flox mice with Col1a2-iCreER mice followed by MI surgery for 4 weeks." (PMID 41168006, 2025). "Compared to the low-fibrosis group, expression of COL1A1 (P = 0.042) and COL1A2 (P = 0.032) was significantly higher in the high-fibrosis group, whereas COL4A4 expression (P = 0.041) was lower." (PMID 41049608, 2025). "Hepatic CCN2 expression was significantly induced in NASH patients with F3–F4 fibrosis and was positively correlated with hepatic Col1A1, Col1A2, Col3A1, or αSMA expression." (PMID 37629004, 2023). "Surprisingly, the hearts of both W and WRF rats showed increased Collagen 1 expression, i.e., W rat heart exhibited signs of fibrosis despite any increase in Col1a1 and Col1a2 expression." (PMID 35236346, 2022). "In contrast, Notch signalling has also been reported to directly upregulate COL1A1 and COL1A2 promoter activity through a Hes1‐dependent mechanism in airway subepithelial fibrosis." (PMID 34363303, 2021). "qPCR analysis showed a decrease in highly upregulated gene levels associated with HSC activation, namely Acta2, Col1a2, Col3a1, TIMP-1, TGF-b, and PDGFR-b, in the neratinib-treated group compared to that in the vehicle-treated fibrosis group." (PMID 32901093, 2020). "Interestingly, the fibrosis markers (Vim, Acta2 and Postn) and ECM genes (Col1a2, Col3a1 and Fn1) were upregulated in YB-1 knockdown mice, demonstrating that knockdown of YB-1 promotes cardiac fibrosis and ECM remodeling." (PMID 31588235, 2019). "RT-PCR also demonstrated a substantial upregulation in the mRNA expression levels of ADAM19 and fibrosis-related genes (COL1A1, COL1A2, and FN1) in the skin tissues of the HOCl-induced fibrosis mouse model compared to controls." (PMID 39716051, 2024). "As we did not see significant lung pathologies in Col1a2 mutants, we set to study the effect of TRF1 deficiency in fibroblasts in the context of a bleomycin (BLM)-induced fibrosis model." (PMID 36202783, 2022). "Indeed, exposure of PCLS from patients with fibrosis or end-stage cirrhosis to Ac-6-FP resulted in a decrease in MAIT cell activation and reduced the expression of fibrogenic genes, including COL1A1 and COL1A2, ACTA2, and TGFB1, together with the number of fibrogenic cells." (PMID 37005415, 2023).
glioma (17 papers, 2009 to 2024). A benign or malignant brain and spinal cord tumor that arises from glial cells (astrocytes, oligodendrocytes, ependymal cells). "As for the specific role of COL1A2 in the tumor microenvironment of glioma and in the immunotherapy process, if further research can be made in this study, it would make this study more valuable in clinical application." (PMID 37354488, 2023). "Our Kaplan–Meier analysis demonstrated that high expression of COL1A1, COL1A2, COL3A1, COL5A1, COL8A1, ELN, FN1 resulted in lower OS in all grade glioma patients, in turn causing poor prognosis." (PMID 36106447, 2022). "Diffuse gliomas with high expression of COL1A2, SAMD9, and KDR had poor prognoses in the CGGA cohort (log-rank test, P < 0.05), which was consistent with the TCGA cohort." (PMID 34815785, 2021). "KDR, COL1A2, and SAMD9 were frequently mutated and highly expressed in gliomas with subtype Ims1." (PMID 34815785, 2021). "Additionally, collagen, type I, alpha 2 (COL1A2) was identified as a hub gene in glioma in several studies." (PMID 34805164, 2021). "In the low-grade gliomas (LGGs), the mRNA expression of COL1A2 and SAMD9 was positively associated with the abundance of B cells (COL1A2: r = 0.163; SAMD9: r = 0.506), macrophages (COL1A2: r = 0.333; SAMD9: r = 0.551), and DCs (COL1A2: r = 0.297; SAMD9: r = 0.571) (P < 0.05)." (PMID 34815785, 2021). "Higher expression of COL1A1, COL1A2, COL3A1, COL4A1, COL4A2, and COL5A2 was negatively correlated with the prognosis of glioma patients." (PMID 38969910, 2024). "On the CGGA website (mRNAseq_325), collagen genes (COL1A1, COL1A2, COL3A1, COL4A1, COL4A2, and COL5A2) in WHO grades II, III, and IV glioma samples were analyzed to explore the expression levels of these genes." (PMID 34034744, 2021). "Then, six collagen genes (COL1A1, COL1A2, COL3A1, COL4A1, COL4A2, and COL5A2) were selected for further validation in Oncomine, TCGA (The Cancer Genome Atlas), and CGGA (Chinese Glioma Genome Atlas) database." (PMID 34034744, 2021). "qPCR analysis of a panel of glioma cell lines with variable Endo180 expression demonstrated substantial expression of both COL1A1 and COL1A2 transcripts in a subset of these cell lines as compared to the minor levels detected in normal brain." (PMID 20339555, 2010). "In detail, COL1A1, COL1A2, COL3A1, COL4A1, and COL4A2 positively correlated with the infiltration of B cells, CD8+T cells, CD4+T cells, macrophages, neutrophils, and dendritic cells in low-grade glioma." (PMID 38969910, 2024). "In addition, we screened the gene COL1A2, which is up-regulated in GBM tissue and closely related to the poor prognosis of glioma patients." (PMID 37354488, 2023). "Additionally, some studies showed that COL1A1, COL1A2, and COL4A1could regulate the immunosuppressive TME of glioma." (PMID 35069551, 2021). "In conclusion, the collagen genes (COL1A1, COL1A2, COL3A1, COL4A1, COL4A2, and COL5A2) could regulate the immunosuppressive microenvironment and be involved in the EMT process of glioma." (PMID 34034744, 2021). "In addition, we conducted intensive study on the COL1A2 gene and found that it not only participates in the regulation of biological behavior of GBM but also may be a key molecule in the TME of glioma." (PMID 37354488, 2023). "Finally, by using gene correlation analysis, we found that the COL1A1, COL1A2, FN1, ITGA1, ITGB1, and ANXA1 genes may play a synergistic role in glioma patients." (PMID 35711921, 2022). "Importantly, we identified that 6 collagen genes (COL1A1, COL1A2, COL3A1, COL4A1, COL4A2, and COL5A2) could regulate the immunosuppressive microenvironment of glioma." (PMID 34034744, 2021).
bladder cancer (16 papers, 2010 to 2025). "COL1A2 has also been reported to be overexpressed in patients with bladder cancer, and its expression levels were positively associated with tumor grade, tumor size, and the depth of invasion." (PMID 39273514, 2024). "The experiments confirmed the causal role of COL1A2 in promoting bladder cancer aggressiveness." (PMID 41561769, 2025). "Functional validation demonstrated that COL1A2 knockdown significantly suppressed bladder cancer cell invasion and migration, while COL1A2 overexpression conversely enhanced invasive phenotypes." (PMID 41561769, 2025). "This COL1A2/ECM/FAK axis constitutes a critical molecular framework underpinning bladder cancer progression and represents a promising therapeutic target for mitigating invasiveness and metastasis." (PMID 41561769, 2025). "The expression level of COL1A2 is dysregulated in several tumors such as malignant melanoma head and neck ovarian pancreatic, and bladder cancer." (PMID 36849997, 2023). "COL1A2 inactivation contributes to increased proliferation and migration activity of bladder cancer and osteosarcoma cells." (PMID 27027429, 2016). "CpG hypermethylation of COL1A2 has been shown to contribute to proliferation and migration activity of human bladder cancer." (PMID 20830311, 2010). "Importantly, these results provide novel insights into the mechanistic underpinnings of bladder cancer invasiveness and position COL1A2 as a promising biomarker and therapeutic target." (PMID 41561769, 2025). "Supported by stringent statistical thresholds (p < 0.05, q < 0.05), these results provide mechanistic insight into how COL1A2 may facilitate bladder cancer progression through modulation of cell–matrix interactions." (PMID 41561769, 2025). "By integrating bioinformatics predictions with experimental validation, we not only delineated COL1A2’s biological function in bladder cancer but also identified it as a potential driver of ECM dysregulation, providing a mechanistic foundation for further exploration." (PMID 41561769, 2025). "Additionally, we assessed the overall survival of bladder cancer patients with high/low COL1A1/COL1A2 expression by analyzing the Cancer Genome Atlas Program (TCGA) databases." (PMID 35694719, 2022). "Furthermore, analysis of the TCGA database correlated a survival benefit with low levels of COL1A1/COL1A2 in bladder cancer patients." (PMID 35694719, 2022). "Collectively, our integrative multi-omics and experimental findings position COL1A2 as a vital molecular driver of NMIBC-to-MIBC progression via ECM pathway activation, underscoring its central role in bladder cancer stage evolution." (PMID 41561769, 2025). "To further elucidate the cellular origin of COL1A2 and its role within the tumor microenvironment, we integrated publicly available single-cell RNA sequencing (scRNA-seq) data (GSE222315) comprising nine bladder cancer patient samples." (PMID 41561769, 2025). "Targeting the COL1A2-mediated ECM remodeling pathway may offer new opportunities to disrupt tumor-stroma interactions and restrain bladder cancer aggressiveness." (PMID 41561769, 2025). "This study reveals that COL1A2 drives the transition from non-muscle-invasive to muscle-invasive bladder cancer via a spatially resolved ECM-FAK signaling axis, delineated through single-cell transcriptomics." (PMID 41561769, 2025). "Collectively, our data delineate a COL1A2-driven signaling axis wherein ECM remodeling activates integrin-FAK signaling cascades, thereby facilitating the transition from non–muscle-invasive to muscle-invasive bladder cancer." (PMID 41561769, 2025). "Given COL1A2’s pivotal role in ECM remodeling and FAK’s essential function in integrin-mediated signal transduction, we evaluated the impact of FAK inhibition on COL1A2-driven invasiveness in SW1710 bladder cancer cells." (PMID 41561769, 2025).
keloid (16 papers, 2008 to 2025). An irregularly shaped, elevated mark on the skin caused by deposits of excessive amounts of collagen during wound healing. "The diagnostic value of COL1A1, COL1A2, COL3A1, COL5A1, and COL5A2 between keloid and different control tissue was evaluated by different datasets." (PMID 35872873, 2022). "Among them, COL1A1 and COL1A2 encode type I collagen and COL3A1 encodes type III collagen, the major components of the extracellular matrix in keloid tissue." (PMID 35872873, 2022). "Indeed, the upregulated PIEZO2 gene expression in keloids aligns with earlier studies demonstrating higher expression of COL1A2 and POSTN in keloids than in normal skin tissue." (PMID 40742741, 2025). "Higher expression levels of COL1A2, PIEZO2, and POSTN were observed in the keloid group compared with the lymphedema group." (PMID 40742741, 2025). "We clustered collagen gene expression in keloids and lymphedema and found that keloid tissue tended to have higher expression of COL3A1, COL1A2, COL1A1, COL6A1, and COL5A1 than did the ML and SL groups." (PMID 40742741, 2025). "RSL3 injection into keloid tissue dramatically decreased the mRNA levels of fibrotic genes, such as α-SMA, COL1A1, COL1A2, COL3A1, and FN1, and downregulated the ECM contents, according to qPCR analysis and the Sircol test." (PMID 40860189, 2025). "Isolated deep lesional fibroblasts display elevated expressions of collagen type I alpha 1 chain (COL1A1), consistent with our findings where COL1A1, COL1A2, COL4A1, and COL5A1 were prominently upregulated in keloid tissues." (PMID 41562114, 2025). "Among the genes enriched in the extracellular region pathway, 24 genes including COL1A1, COL1A2, and COL4A1 were significantly upregulated in keloid tissues." (PMID 41562114, 2025). "First, the expressions of genes highly upregulated in keloid tissue, IL-6, CTGF and COL1A2, were enhanced in keloid marginal fibroblast–transplanted tissue, and this expression was suppressed by vismodegib." (PMID 38062202, 2023). "In our study, the results of ENCORI prediction and RT-qPCR showed that miR-29a-3p can regulate the expression of COL1A1, COL1A2, COL3A1, COL5A1, and COL5A2, and these target genes were closely related to the development of keloid." (PMID 35872873, 2022). "Genes involved in extracellular matrix formation including COL1A1, COL3A1, POSTN, COL1A2, FN1, and ASPN were significantly upregulated in keloid compared to the normal skins." (PMID 35990663, 2022). "It was downregulated in keloid and can negatively regulate the expression of COL1A1, COL1A2, COL3A1, COL5A1, and COL5A2." (PMID 35872873, 2022). "Transcriptome analysis showed that the core differentially expressed genes related to collagen synthesis play a vital role in the pathogenesis of keloids, including COL1A, COL1A2, COL5A2, and COL3A1." (PMID 35222522, 2021). "The hub genes of COL1A, COL1A2, COL5A2, and COL3A1 indicate that genes related to collagen synthesis play a vital role in the pathogenesis of keloids." (PMID 35222522, 2021). "In contrast, collagen type 1 alpha 2 (COL1A2) and ER stress-related genes (ATF4, CHOP, ERK, and IRE1α) were significantly upregulated in the keloid tissues." (PMID 34639105, 2021). "Lipo-PGE1 also decreased COL1A1, COL1A2, and COL3A1 mRNA expression and the total soluble collagen level in keloid fibroblasts." (PMID 28644845, 2017). "In contrast, COL1A1, COL1A2, and POSTN expression levels were significantly increased in wounded keloid ESS." (PMID 22536458, 2012). "When the diagnostic value of these key genes were evaluated between the normal skin from keloid-prone or normal individuals (GSE113619), the AUC values of COL1A1, COL1A2, COL3A1, COL5A1, and COL5A2 in keloid were 0.650, 0.625, 0.575, 0.525, and 0.450, respectively." (PMID 35872873, 2022).
keloid (continued). "They determined that only 25 common dysregulated genes were in keloids in 7 studies where collagen, type I, alpha 1 (COL1A1); collagen, type I, alpha 2 (COL1A2); collagen, type V, alpha 2 (COL5A2); and collagen, type VI, alpha 1 (COL6A1) were systematically upregulated." (PMID 33860039, 2021). "Interestingly, the expression of collagen type I alpha 2 chain (COL1A2) was not significantly different between keloid fibroblasts and immature scar fibroblasts (P = 0.23)." (PMID 38622256, 2024). "As a result, there were 25 known keloid-related genes reported among the analyzed genes, whereas two pairs of them (COL14A1 and TNC, COL1A2 and PEPD) were co-occurred in the literature that mentioned the curated keyword 'keloid' (data not shown)." (PMID 18620599, 2008).
heart failure (15 papers, 2016 to 2025). Inability of the heart to pump blood at an adequate rate to meet tissue metabolic requirements. "According to the validated datasets, Stat4 and Col1a2 were particularly strongly associated with the comorbidity of heart failure and depression." (PMID 39295096, 2024). "Heart histological staining and mRNA levels of genes associated with heart failure (Acta1 and Nppa), inflammation (IL‐6), and fibrosis (Ctgf, Col1a2, Timp1, and Mmp9) were assessed." (PMID 32133617, 2020). "Heart failure comorbid with depression may be associated with five hub genes, including Stat4, Cd83, Cx3cr1, Col1a2, and Sh2d1b." (PMID 39295096, 2024). "The results show that a total of 5 pivotal genes, CD83, CX3CR1, STAT4, COL1A2, and SH2D1B, of which STAT4 and COL1A2 are important underlying the co-morbidity mechanism of heart failure and depression." (PMID 38084332, 2023). "Pressure-volume loop analysis and RNA expression analysis of Rcan-1, ANP, and BNP as heart failure and hypertrophy markers; Col1a2 as a fibrosis marker; and SERCA2a and PLB as calcium regulatory markers were performed after 4 weeks of administration of 0.2% DS37001789 in TAC mice." (PMID 32055741, 2020). "Concomitantly with cardiac dysfunction and heart failure, Tg-SCD hearts displayed the significant up-regulation of two major cardiac collagens, which are of type 1 and type 3, i.e., Col1a2 and Col3a1." (PMID 34576047, 2021). "Furthermore, we observed the proportion of markers associated with fibroblasts (VIM, POSTN, DDR2, THBS4, COL1A1, COL1A2, FN1) were significantly higher in heart failure than the control group in the human data, which were consistent with that in mice." (PMID 36805782, 2023). "In addition, in our analysis results, NPPA, NPPB, COL1A2, ASPN, ANKRD1 and CTGF were all confirmed to be closely related to heart failure in dilated cardiomyopathy in various studies." (PMID 34970603, 2021). "In addition, up-regulation of extracellular matrix proteins, Col1a2 and Col3a1, could reflect adverse fibrotic remodeling of Tg-SCD mice with symptoms of heart failure." (PMID 34576047, 2021).